ICAM1 (intercellular adhesion molecule 1)
Diseases named in the same sentence as ICAM1 in open-access papers (continued):
Sharing a sentence is not in itself a finding about the gene and the disease.
atherosclerosis (continued). "Accumulating evidence suggests that the induction of VCAM-1 or ICAM-1 by TNF-α in endothelium is mediated by the activation of MAPK and transcription factors such as NF-κB, leading to the pathogenesis of atherosclerosis." (PMID 23401716, 2013). "Levels of soluble E-sel, ICAM-1 and VCAM-1 in blood plasma were significantly higher in patients with unstable angina, acute coronary syndrome and atherosclerosis." (PMID 23895132, 2013). "It is well established that E-sel, VCAM-1, ICAM-1 and MCP-1are key molecules involved in the initiation of inflammation pathogenesis of atherosclerosis, they collaboratively promote the adhesion of monocytes and then the migration to endothelium." (PMID 23895132, 2013). "We and others have also shown that under conditions of atherosclerosis progression, proteins such as VCAM-1 and ICAM-1 are up-regulated." (PMID 22761902, 2012). "During the early stages of atherosclerosis progression endothelial cells express adhesion molecules (e.g. VCAM-1, ICAM-1, E-selectin) as well as chemokines (e.g. MCP-1, MCP-3, Fractalkine) upon activation of the nuclear factor-kappa B." (PMID 22383985, 2012). "There were statistically significant reductions in the levels of ICAM-1, VCAM-1 and CRP at the end of treatment with water extract in group 500 mg/kg compared to atherosclerosis group." (PMID 21214952, 2011). "The expression of the adhesion molecules intercellular adhesion molecule-1 (ICAM-1) and vascular cell adhesion molecule-1 (VCAM-1) in endothelial cells is the earliest known event in the initiation and progression of atherosclerosis." (PMID 21980456, 2011). "Our data emphasize the contribution of ICAM-1 dynamics to its adhesive function and may therefore represent an interesting target for future therapies to reduce leukocyte accumulation to the vessel wall, as occurs in diseases such as atherosclerosis and rheumatoid arthritis." (PMID 20596527, 2010). "Initial leukocyte rolling is mediated by E- and P-selectin whereas firm adhesion to the vascular wall is mediated via integrin binding with intercellular adhesion molecule-1 (ICAM-1) and VCAM-1, with the latter more important in initiation of atherosclerosis." (PMID 19883911, 2010). "The unaltered expression of ICAM-1 and VCAM-1 corresponds well with the unaltered ICAM-1 and VCAM-1 mRNA levels in the CB exposed mice of either age group as well as the unchanged progression of atherosclerosis in the aged CB exposed mice." (PMID 21054825, 2010). "Thus CRP, ET-1,P-selectin, ICAM-1, and VCAM-1 levels are related to bothhyperglycemia and dyslipidemia and may reflect the presence of amultiple-risk factor clustering syndrome providing further supportfor the role of these markers in atherosclerosis." (PMID 17497038, 2007). "In this study, hypoglycemia did not result in changes in VEGFA, ICAM1, ICAM2 and VCAM1 as known mediators of endothelial dysfunction associated with atherosclerosis, stroke and myocardial infarction, as well as T2D microvascular complications." (PMID 41596469, 2026). "Animal studies indicate that mild hyperbilirubinemia prevents atherosclerosis progression by improving lipid profiles and modulating the mRNA expression of vascular cell adhesion molecule 1 (VCAM-1), ICAM-1, inducible nitric oxide synthase (iNOS), and lectin-like LDL receptor 1 (LOX-1)." (PMID 40612433, 2025). "In an atherosclerosis mouse model, taurine was shown to reduce LDL oxidation and protect endothelial cells from oxidative stress and apoptosis and reduce adhesion molecules like ICAM‐1, further supporting its protective cardiovascular role." (PMID 40620033, 2025). "Previous studies showed that RETN could accelerate the process of atherosclerosis by upregulating vascular endothelial adhesion factors such as VCAM-1 and ICAM-1." (PMID 40641746, 2025).
atherosclerosis (continued). "In light of studies showing that FOXP1 can transcriptionally repress the NLRP3 inflammasome and inhibit the development of atherosclerosis, we hypothesized that CtBP1 might interact with FOXP1 to modulate VCAM‐1 and ICAM‐1 gene transcription." (PMID 39949978, 2025). "Endothelial dysfunction molecular markers, including intercellular adhesion molecule-1 (ICAM-1) and tumor necrosis factor-α (TNF-α), which are pivotal factors in the development and pathophysiology of atherosclerosis, exhibit increased levels in individuals with prediabetes." (PMID 40251690, 2025). "Inflammation and lipid abnormalities promote endothelial activation which is characterized by an increase in the adhesion molecules ICAM-1 and VCAM-1, which facilitates the recruitment of monocytes to the endothelium, initiating and accelerating the development of atherosclerosis." (PMID 40003621, 2025). "While ICAM-1 is constitutively expressed at a low basal level on ECs, its levels are augmented by inflammatory cytokines (TNF-α, IL-1, and IFN-γ) in diseased states such as atherosclerosis." (PMID 40630903, 2025). "ICAM-1 and VCAM-1 are intermittently expressed in endothelial cells and smooth muscle cells in normal arteries, with a high density in plaque-prone locations, and play a significant role in atherosclerosis and endothelial dysfunction." (PMID 40224490, 2025). "This leads to decreased expression of vascular cell adhesion molecule-1 (VCAM-1) and intercellular adhesion molecule-1 (ICAM-1) in endothelial cells, reduced adhesion of monocytes to endothelial cells, and ultimately inhibiting the initiation and progression of atherosclerosis." (PMID 41011612, 2025). "Recent studies in healthy populations have associated IL-32 with atherogenic lipoproteins and with monocyte endothelial adhesion mediated by intercellular adhesion molecule-1 (ICAM-1) and vascular cell adhesion molecule-1 (VCAM-1), a crucial step in atherosclerosis pathogenesis." (PMID 40299461, 2025). "ICAM-1 levels have been reported to be independent of age, sex, diabetes mellitus, and the degree of atherosclerosis." (PMID 39091977, 2024). "Cell adhesion molecules (CAMs), such as ICAM-1 and VCAM-1, are produced by inflammatory cytokines; their levels indicate the inflammatory process occurring in the vascular endothelium; these are also considered early indicators of atherosclerosis." (PMID 39457107, 2024). "Additionally, Tat induces the expression of both vascular cell adhesion protein-1 (VCAM-1) and intercellular adhesion molecule-1 (ICAM-1), inferring a potential mechanism via which HIV-1 intensifies endothelial injury as well as atherosclerosis." (PMID 38411777, 2024). "Our in vivo findings demonstrated that FCBP effectively mitigates weight gain in a dose-dependent manner and reduces inflammatory markers (ICAM-1 and VCAM-1) in endothelial cells, suggesting its role in managing diet-induced obesity and preventing early atherosclerosis." (PMID 39534464, 2024). "Moreover, exercise as a nonpharmacological method improves vascular inflammation and reduces the expression of factors involved in inflammation, including ICAM-1 and VCAM-1, ultimately preventing the progression of atherosclerosis." (PMID 39742025, 2024). "Inflammatory modulators/biomarkers, such as IL-1α, IL-1β, IL-6, IL-12, IL-15, IL-18, and tumor necrosis factor α, or alternative anti-inflammatory cytokine IL-10, and adhesion molecules (ICAM-1, VCAM-1), involved in atherosclerosis progression have been shown to predict cardiovascular diseases." (PMID 37374202, 2023). "Through analysis of protein functional enrichment, it was found that AR may act on IL-6, TNF-α, ICAM-1, VCAM-1, and MCP-1 and play anti-atherosclerosis and neuroprotective roles." (PMID 37361203, 2023).
atherosclerosis (continued). "Some other inflammatory factors such as monocyte chemoattractant protein-1 (MCP-1), intercellular adhesion molecule-1 (ICAM-1), and vascular cell adhesion molecule-1 (VCAM-1) play crucial role in recruitment of inflammatory monocytes into vascular wall and initiate atherosclerosis." (PMID 36627567, 2023). "As HCAECs are derived from a vessel known to develop atherosclerosis while HUVECs are not, we now focused on regulation of ICAM-1 in HCAECs." (PMID 37179303, 2023). "ICAM-1 and VCAM-1 overexpression promotes ED, which is an early stage of atherosclerosis." (PMID 37374202, 2023). "Dysfunctional ECs are activated; thus, expressing adhesion molecules such as vascular cell adhesion molecule (VCAM-1) and intercellular adhesion molecule 1 (ICAM-1), which in turn start to recruit inflammatory cells contributing to the progression of the atherosclerosis." (PMID 36838850, 2023). "Some results have indicated a role for VCAM-1 in driving atherosclerosis without a requirement for ICAM-1." (PMID 37237555, 2023). "Increases in the amount of PA observed in the AE group and higher CRF in the COMB group were related to reduced levels of ICAM-1, which is a pro-inflammatory molecule promoted by IGF and TNF-α and highly expressed in endothelial cells and related to atherosclerosis." (PMID 35529777, 2022). "EBV may also be involved in the atherosclerosis by triggering IL-6 and TNF-α secretion by macrophages, intercellular adhesion molecule-1 (ICAM-1) expression on ECs and lipid profile alternations in blood." (PMID 36059478, 2022). "Senescent ECs may promote monocyte recruitment to vascular endothelium via increased MCP-1, ICAM-1, or VCAM-1 in the early stage of atherosclerosis and may increase thrombosis via activated PAI-1." (PMID 36232471, 2022). "This resulted in the upregulation of ICAM-1 on endothelial cells through the activation of TNF-α/NF-κB signalling pathways, which promotes the adhesion of monocytes to ECs, a key event in the initiation of atherosclerosis." (PMID 35736920, 2022). "Clinical studies included a more extensive list of diverse biomarkers associated with atherosclerosis development to include TNF-α, VCAM-1, ICAM-1, and several interleukins, which were not as extensively studied in observational studies." (PMID 36232062, 2022). "When examining atherosclerosis in a diabetic mouse model, H2S inhibited the formation of aortic root plaques, and downregulated the levels of vascular cell adhesion molecule 1 (VCAM1) and intercellular adhesion molecule 1 (ICAM1)." (PMID 35563208, 2022). "Investigations of IL-33 in atherosclerosis revealed that this cytokine stimulates the expression of the endothelial adhesion molecules VCAM1, ICAM1 and E-selectin as well as the expression of CCL2 in HUVECs in a concentration-dependent manner resulting in increased leukocyte adhesion." (PMID 35600479, 2022). "It is observed that, in comparison with the control group, the endothelium of apoE-/- mice with S1 or S3 treatment showed less TUNEL positive area and decreased ICAM-1 and VCAM-1 protein level, suggesting S1 and S3 inhibited endothelium injury during atherosclerosis development." (PMID 35335352, 2022). "In sum, endothelial NCK2 signaling promotes atherosclerosis progression, but not initiation, through a mechanism that involves increased expression of ICAM-1 in the arterial wall and neointimal/intimal layers." (PMID 36035930, 2022). "The concentration of intercellular adhesion molecule –1 (ICAM-1), which promotes endothelial damage and atherosclerosis, did not increase in the KD group, in contrast to the LF diet group." (PMID 35669612, 2022). "Three key pathways (pathways in cancer, the TNF signaling pathway, and lipid and atherosclerosis) and the top six anti-COVID-19 core targets (IL-6, PPARG, MAPK3, PTGS2, ICAM1, and MAPK1) were determined to be involved in the treatment of COVID-19 with active phytomolecules of Kochiae Fructus." (PMID 35992697, 2022).
atherosclerosis (continued). "There are many key molecules involved in the laminar shear stress and atherosclerosis pathways, such as endothelin 1 (EDN1), vascular cell adhesion molecule 1 (VCAM1), KLF2, intercellular adhesion molecule 1 (ICAM1), and platelet and endothelial cell adhesion molecule 1 (PECAM1)." (PMID 36364780, 2022). "In the early step of atherosclerosis, activated ECs release chemokines (eg. monocyte chemotactic protein 1, MCP-1) and adhesion molecules (eg., intercellular adhesion molecule 1, ICAM1 and vascular cell adhesion molecule 1, VCAM1), inducing the attachment of monocytes to the arterial vessel wall." (PMID 36160452, 2022). "In summary, we determined that ITGAM, TYROBP, ICAM1 and CAMP may possess significant roles in mediating the chronic inflammatory process that eventually culminates in atherosclerosis and CAD." (PMID 33758323, 2021). "ECD is initiated by multiple inflammatory factors in atherosclerosis; when the endothelium is injured, inflammatory mediators, including vascular cell adhesion molecule-1 (VCAM-1), intercellular adhesion molecule-1 (ICAM-1), interleukin 6 (IL-6), and tumor necrosis factor α (TNF-α)are expressed." (PMID 34899318, 2021). "During the genesis of atherosclerosis, inflammation induces endothelial cells to express adhesion molecules vascular cell adhesion protein 1 (VCAM-1), intercellular adhesion molecule 1 (ICAM-1), and E-selectins which leads to the adhesion of monocytes to endothelial cells." (PMID 33996157, 2021). "Release of ICAM-1 from vascular endothelial cells was reduced with PCSK9i alirocumab and anti-PCSK9 vaccine AT04 in the APOE∗3Leiden.CETP transgenic mouse model for hyperlipidemia and atherosclerosis." (PMID 34336112, 2021). "Earlier studies reported a relationship between ICAM-1 and CIMT as subclinical atherosclerosis risk, which concluded that ICAM-1is independent of other known CHD risk factors and is strongly associated with carotid plaques." (PMID 34191823, 2021). "The opposite effect was observed in a fluoxetine-treated (for 4 weeks) mouse model of atherosclerosis, which showed an increased expression of ICAM-1 on neutrophils and monocytes, but not endothelial cells." (PMID 33945102, 2021). "Adhesion molecules such as VCAM-1 and ICAM-1 and chemokines such as MCP-1/JE and CXCL1/KC are important modulators in monocyte recruitment, rolling, and adhesion to the vascular endothelium and play a fundamental role in the pathogenesis of atherosclerosis." (PMID 34830366, 2021). "Both ICAM‐1 and VCAM‐1 accelerate the development of various diseases such as atherosclerosis." (PMID 31993189, 2020). "Similarly, there is evidence that TGF-β played an anti-atherosclerosis role for its partial disruption of vascular cell adhesion molecule 1 (VCAM-1), and intercellular adhesion molecule 1 (ICAM-1) expression in mouse models of accelerated atherosclerosis." (PMID 33276745, 2020). "CoQ10 could also inhibit the inflammatory proteins such as IL-6, TNF-α, ICAM-1, VCAM-1 and NLRP3, thus exerting the role inhibiting atherosclerosis." (PMID 32792941, 2020). "Moreover, curcumin reduces NF-κB, affecting gene regulation, and decreases the TNFα-induced expression of intercellular adhesion molecule-1 (ICAM-1), monocyte chemoattractant protein-1 (MCP-1), and IL-8 mRNA, characteristic of the atherosclerosis process." (PMID 32707934, 2020). "HU enhanced MCP‐1, ICAM‐1 and VCAM‐1 as shown in serum level and protein expression, suggesting that these three molecules are also involved in a HU‐driven atherosclerosis promoting effect that would exacerbate the pathogenesis of atherosclerosis." (PMID 30690853, 2019). "Studies in ApoE−/− mice indicate that supplementation with curcumin leads to less macrophage infiltration in atherosclerosis plaque, reduced aortic NF-κB activation, reduced levels of IL-1B and TNF-α, and reduced expression of the adhesion molecules ICAM-1 and VCAM-1." (PMID 30518065, 2018).
atherosclerosis (continued). "Endothelial activation, characterized by excessive cytokines (IL-6 and IL-8) production and adhesion molecules (ICAM-1 and VCAM-1) expression, is a crucial factor in the development of atherosclerosis and SCFA regulated endothelial activation in different ways." (PMID 29615908, 2018). "Excessive expression of ICAM-1 and VCAM-1 is regarded as an early event of atherosclerosis." (PMID 29615908, 2018). "Our mAb recognizes the C-terminal sequence of the HMGB1 molecule and can neutralize the intercellular adhesion molecule 1 (ICAM1)-inducing activity of HMGB1 in vitro;19 moreover, therapeutic effects against brain stroke, atherosclerosis, and viral infections have also been reported." (PMID 28649578, 2017). "Atherosclerosis in HAD rats was characterized by marked increases in aortic monocyte chemotactic factor-1 (MCP-1), intercellular adhesion molecule-1 (ICAM-1), and vascular cell adhesion molecule-1 (VCAM-1) mRNA compared with the ND group, according to real-time PCR." (PMID 26783398, 2016). "The first step of atherosclerosis is activation of endothelial cells, which elaborate adhesion molecules such as vascular cell adhesion molecule‐1 (VCAM‐1), intercellular adhesion molecule 1 (ICAM‐1) and E‐selectin." (PMID 27515767, 2016). "Therefore, VCAM-1 seems to have a more crucial role than ICAM-1 in the two major mechanisms leading to increased LVMI, i.e. atherosclerosis and hypertension." (PMID 26398099, 2015). "Cellular adhesion molecules, including ICAM-1 and VCAM-1, are over-expressed by the vascular endothelium in the initial process of atherosclerosis, which may lead to upregulation of endothelium cell adhesion and atherosclerotic lesions." (PMID 25933220, 2015). "Elevated CRP serum levels may promote atherosclerosis through its effect on adhesion molecule expression, since it has been shown that CRP induces ICAM-1 expression in coronary artery endothelial cells." (PMID 25490200, 2014). "In apoE knockout rats, occlusal disharmony may induce VCAM1, ICAM1 and TLR4 expression and accelerate the initiation of atherosclerosis." (PMID 25189624, 2014). "In vivo administration of A-285222 completely blocked diabetes-induced NFAT-transcriptional activity in the aorta, leading to reduced expression of IL-6, OPN, MCP-1, ICAM-1, CD68 and TF, all established players in atherogenesis, as well as to reduced diabetes-induced atherosclerosis." (PMID 23755169, 2014). "In fact, previous studies have reported that some components of the MD such as EVOO or nuts may down-regulate inflammatory markers related to atherosclerosis such as VCAM-1, ICAM-1, E- and P-Selectin, CRP and IL-6." (PMID 24925270, 2014). "One of the earliest events during the initiation of atherosclerosis is the high expression of adhesion molecules by vascular endothelial cells, including vascular cell adhesion molecule-1 (VCAM-1) and intercellular adhesion molecule-1 (ICAM-1)." (PMID 24722330, 2014). "In conclusion, in the apoE knockout rats, occlusal disharmony may induce VCAM1, ICAM1 and TLR4 expression and accelerate the initiation of atherosclerosis." (PMID 25189624, 2014). "Levels of serum IL-1β and TNF-a dropped, mRNA and protein expression of E-sel, VCAM-1, ICAM-1 and MCP-1 in the aorta of rabbits were respectively down-regulated by the treatment of kaempferol, indicating that kaempferol can prevent atherosclerosis by alleviating vascular inflammation." (PMID 23895132, 2013). "Because ICAM-1 deficiency was previously found to protect from atherosclerosis in mice and because SGEF acts downstream of ICAM-1 to facilitate the formation of docking-structures on endothelial cells, we sought to investigate the role of SGEF in a mouse atherosclerosis model." (PMID 23372835, 2013).